HOXD12 (homeobox D12)
Description:
Sequence-specific transcription factor which is part of a developmental regulatory system that provides cells with specific positional identities on the anterior-posterior axis.
Synonyms: HOX4H
Tractability: No criterion of Open Targets' tractability assessment is met for any kind of drug.
Gene: Protein-coding gene on chromosome 2 (176,099,795 to 176,102,489, forward strand). Ensembl gene ENSG00000170178.
Subcellular location: Nucleus
Gene Ontology:
Molecular function: protein binding; sequence-specific double-stranded DNA binding; DNA-binding transcription factor activity, RNA polymerase II-specific; DNA binding
Biological process: regulation of DNA-templated transcription; regulation of transcription by RNA polymerase II
Cellular component: chromatin; nucleus; transcription regulator complex
Genetic constraint (gnomAD): Loss-of-function variants: 21 observed, 17.78 expected, observed/expected ratio (o/e) 1.18, 90% interval 0.84 to 1.68. The upper end of that interval is the gene's LOEUF score, 1.68, which puts it in group 6 of 6, group 1 being the genes least tolerant of losing a copy. Missense variants: 472 observed, 360.42 expected, observed/expected ratio (o/e) 1.31, 90% interval 1.21 to 1.41. Synonymous variants: 196 observed, 171.53 expected, observed/expected ratio (o/e) 1.14, 90% interval 1.02 to 1.29.
Homologues: Orthologues: chimpanzee HOXD12 (99% identical), macaque HOXD12 (98% identical), rabbit HOXD12 (94% identical), dog HOXD12 (91% identical), guinea pig HOXD12 (91% identical), pig HOXD12 (91% identical), rat Hoxd12 (86% identical), mouse Hoxd12 (86% identical), zebrafish hoxd12a (43% identical). Paralogues in human: HOXC12 (43% identical), HOXD9 (27% identical), HOXA10 (24% identical), HOXD10 (24% identical), HOXC10 (23% identical), HOXC9 (23% identical), HOXB9 (22% identical), HOXC11 (21% identical), HOXA11 (19% identical), HOXB1 (19% identical), HOXD1 (19% identical), HOXD3 (19% identical), and 30 more.
Diseases named in the same sentence as HOXD12 in open-access papers:
HOXD12 is named in the same sentence as 19 diseases in open-access papers, as found by Europe PMC text mining. Sharing a sentence is not in itself a finding about the gene and the disease. The quoted sentences say what the papers report.
clubfoot (2 papers, 2023 to 2024). The most common congenital deformation of the foot, occurring in 1 of 1,000 live births. "Initially, genes associatedwith clubfoot (PITX1, TBX4, HOXA9, HOXD10, HOXD12,HOXD13, HOXA9, TPM1, TPM2, COL9A1, FLNB, CASP8,CASP10, UTX, CHD1, RIPPLY2, CAND2, WNT7) werescreened for potential variants." (PMID 38952703, 2024). "HOXD12 and HOXD13 single nucleotide polymorphisms (SNPs) have been associated with idiopathic clubfoot." (PMID 37964341, 2023).
glioma (2 papers, 2017 to 2023). A benign or malignant brain and spinal cord tumor that arises from glial cells (astrocytes, oligodendrocytes, ependymal cells). "Analysis of HOXD gene expression in human low-grade gliomas tissues revealed that HOXD1 and HOXD12 were highly expressed in gliomas, whereas the expression of HOXD3 was depressed." (PMID 29383189, 2017). "Another research examined the expression of HOXD family genes by QPCR in 14 pediatric low-grade gliomas and found that HOXD1 and HOXD12 were overexpressed in tumor tissue compared to non-neoplastic tissues, while HOXD3 presented lower expression in grade I glioma." (PMID 37547473, 2023).
melanoma (2 papers, 2016 to 2021). A malignant, usually aggressive tumor composed of atypical, neoplastic melanocytes. "For instance, high levels of promoter methylation correlated with active expression of EBF3, MGMT, HOXD12 and GATA4 in melanoma, indicating other factors may affect the relations of DNA methylation with transcriptional activity." (PMID 34013637, 2021). "Likewise, the function of HOXD12 has not been defined, but it has been shown to be silenced in melanoma cells through the methylation of its promoter." (PMID 26867567, 2016).
neuroblastoma (2 papers, 2012 to 2022). Neuroblastoma (NB) is the most common solid, extracranial childhood tumor. "In this study, we show that individual induction of HOXD8, HOXD9, HOXD10 or HOXD12 in neuroblastoma cells is able to recapitulate RA-induced differentiation phenotype." (PMID 22879880, 2012). "Similarly, several HOX genes including HOXD11 and HOXD12 which are known to be ATRA responsive in neuroblastoma cells, and to be able to induce growth arrest and differentiation in these cells, were significantly induced in WT but to a lesser degree or were not induced in BKO98 cells." (PMID 35831557, 2022). "Notably, the four human HOXD proteins (HOXD8, HOXD9, HOXD10, HOXD12) with both anti-growth and differentiation-inducing activities in neuroblastoma cells correspond to the Drosophila Hox proteins abd-A (HOXD8) and Abd-B (HOXD9, HOXD10, HOX12) that are responsible for specifying the abdomen." (PMID 22879880, 2012). "Together, these findings demonstrate distinct functions of HOXD proteins in regulation of neuroblastoma cell proliferation, with only HOXD3, HOXD8, HOXD9, HOXD10 and HOXD12 proteins being able to recapitulate the G1 arrest phenotype induced by RA." (PMID 22879880, 2012).
cleft palate (1 paper, 2021). Cleft palate is a fissure type embryopathy that affects the soft and hard palate to varying degrees. "This comprehensive analysis revealed decreases in gene expressions associated with lung development; Foxa2, Notch1, Foxp2, Nkx2.1, and intestine development; Cdx2, Foxf2, Foxl1, and skeletal development; Hoxd12, Hoxd13, Scx, Brachyury, and cleft palate; Foxf2." (PMID 34671097, 2021).
colon cancer (1 paper, 2022). "The role of posterior HOXD genes in colon cancer is not well defined; HOXD8 and HOXD12 expression are reduced in colon cancer, whereas HOXD10 expression may be increased." (PMID 35015732, 2022).
cystic teratoma (1 paper, 2024). "In summary, amplifications of EVX2, HOXD13, HOXD12, HOXD11, HOXD10, and HOXD9 on 2q31.1, NDUFV1 on 11q13.2, and RPL10, SNORA70, DNASE1L1, TAZ, ATP6AP1, and GDI1 on Xq28 were found in all nine mature cystic teratomas in this study." (PMID 38907278, 2024). "The most interesting findings of this study are amplifications of EVX2, HOXD13, HOXD12, HOXD11, HOXD10, and HOXD9 on a 41.6 kb segment of 2q31.1 in all nine mature cystic teratomas." (PMID 38907278, 2024).
lymph node metastasis (1 paper, 2017). "High FIGO stage also highly correlated with high HOXB7 expression, and lymph node metastasis was found to be associated with high HOXD12 and HOXD13 expression (P < 0.01)." (PMID 29137433, 2017).
mesothelioma (1 paper, 2016). A usually malignant and aggressive neoplasm of the mesothelium which is often associated with exposure to asbestos. "One of the most striking differences is the expression of HOXC12 and HOXD12 by Met-5a but not by any of the mesothelioma cell lines." (PMID 26867567, 2016).
oligodendroglioma (1 paper, 2024). A well-differentiated (WHO grade II), diffusely infiltrating neuroglial tumor, typically located in the cerebral hemispheres. "Overall, elevated HOXD12 expression and gene body hypermethylation were associated with an older, atypically aggressive subtype of oligodendroglioma." (PMID 39259414, 2024). "Overall, HOXD12 expression and gene body hypermethylation were associated with an older, atypically aggressive subtype of oligodendroglioma." (PMID 39259414, 2024). "We propose that HOXD12 expression and gene body hypermethylation are molecular features associated with poor prognoses that may be linked to two age-associated subtypes of oligodendroglioma." (PMID 39259414, 2024). "Accordingly, we hypothesized that HOXD12 hypermethylation would be more prevalent in older oligodendroglioma patients and associated with poor survival." (PMID 39259414, 2024). "We propose that future biomarker-driven clinical trials of oligodendroglioma collect HOXD12 gene body methylation data, possibly through whole-genome DNA methylation profiling." (PMID 39259414, 2024). "Patients harboring HOXD12-positive expression status and HOXD12 gene body hypermethylation in the TCGA formed the class of oligodendrogliomas with the worst outcomes, with a median overall survival of only 2.6 years." (PMID 39259414, 2024). "Having shown that HOXD12-positive expression status and HOXD12 gene body hypermethylation were markers for poor survival in oligodendroglioma, we interrogated their relationship with clinically relevant histopathologic, genomic, and radiographic features in the TCGA." (PMID 39259414, 2024). "The group of oligodendroglioma tumors with high HOX gene body DNA methylation levels was associated with poor survival, older patients, and more aggressive histology and was best differentiated from the HOX-low group by genes in the HOXD locus, especially HOXD12." (PMID 39259414, 2024). "Unfortunately, immunohistochemistry for HOXD12 was not a sufficiently sensitive surrogate marker to detect a difference between HOXD12 gene body methylation levels in a small set of oligodendrogliomas (N = 10)." (PMID 39259414, 2024).
teratocarcinoma (1 paper, 2024). A germ cell tumor characterized by the presence of an embryonal carcinoma component and a teratoma component. "Only one previous study on teratocarcinoma embryoid bodies has suggested a possible role for HOXD12 in establishing extraembryonic endoderm lineage in mice." (PMID 38907278, 2024).
cancer (4 papers, 2015 to 2025). A tumor composed of atypical neoplastic, often pleomorphic cells that invade other tissues. "For instance, the TSS of several developmental-related and cluster 2 genes, such as GATA4, HOXD11, and HOXD12, was hypermethylated in a variety of cancer types." (PMID 35580989, 2022). "Progesterone receptor positive cancer tissues have higher levels of HOXD12 and D13 than negative cancer tissues in BRCA." (PMID 36213580, 2022). "Furthermore, we found reactivation of HOXD12 and HOXD13 expression in selected cancer samples and, surprisingly, a strong positive correlation between HOTAIR and HOXD12, particularly in overexpressing UC tissues (r Pearson = 0.92)." (PMID 25994132, 2015).
tumor (3 papers, 2022 to 2025). "However, other genes, such as HOXB1, HOXC5, HOXC12, HOXD3, and HOXD12, have extremely low expression levels, suggesting that they are more expressed in normal tissue samples than in tumor samples." (PMID 39980564, 2025). "To highlight these features, we identified a representative tumor harboring both HOXD12-positive expression status and HOXD12 gene body hypermethylation that displays mitotic figures, necrosis, and MVP, as well as contrast enhancement and substantial peritumoral edema." (PMID 39259414, 2024). "Similarly, HOXD12-positive expression status was independently prognostic of all testable radiographic features (total tumor volume omitted due to collinearity)." (PMID 39259414, 2024). "Remarkably, HOXD12 gene body hypermethylation was prognostic independent of HOXD12 expression, as well as patient age and tumor WHO grade." (PMID 39259414, 2024).
HOXD12 also shares sentences with these, for which no sentence is quoted: celiac disease (2 papers); leukemia (2); amyotrophic lateral sclerosis (1); mammary tumours (1); renal carcinoma (1); teratoma (1).